FILNC1 (FOXO induced long non-coding RNA 1)
Gene: Long non-coding RNA gene on chromosome 6 (139,677,639 to 139,860,476, forward strand). Ensembl gene ENSG00000231426.
Diseases named in the same sentence as FILNC1 in open-access papers:
FILNC1 is named in the same sentence as 5 diseases in open-access papers, as found by Europe PMC text mining. Sharing a sentence is not in itself a finding about the gene and the disease. The quoted sentences say what the papers report.
renal carcinoma (4 papers, 2017 to 2022). A carcinoma arising from the epithelium of the renal parenchyma or the renal pelvis. "FILNC1 deficiency in renal cancer cells alleviates energy stress-induced apoptosis and markedly promotes renal tumor development." (PMID 28978906, 2017). "Under energy stress, FOXO upregulates FOXO-induced lncRNA 1 (FILNC1) to suppress proliferation and induce apoptosis of renal cancer cells." (PMID 36230902, 2022). "Together, our study not only identifies FILNC1 as a negative regulator of renal cancer with potential clinical value, but also reveals a regulatory mechanism by long non-coding RNAs to control energy metabolism and tumor development." (PMID 28978906, 2017). "A survey of renal cancer RNA-seq data set from TCGA confirmed downregulation of FILNC1 expression in renal cancer samples compared with normal kidney samples." (PMID 28978906, 2017). "Kaplan–Meier analysis showed that renal cancer patients with FILNC1-low tumors had worse overall survival than those with FILNC1-high tumors." (PMID 28978906, 2017). "Oncomine expression analysis comparing FILNC1 expression levels between tumors and corresponding normal tissues revealed that FILNC1 was most downregulated in renal cancers." (PMID 28978906, 2017). "Together, these analyses provided strong rationale for our study of c-Myc in the context of FILNC1 function in renal cancer." (PMID 28978906, 2017). "Together, our data showed that FILNC1 is highly expressed in kidney and downregulated in renal cancers, and that renal cancer patients with low expression of FILNC1 have poor clinical outcomes, providing further support of our functional data." (PMID 28978906, 2017). "Functional analyses revealed that overexpression of FILNC1 #1 in 769P cells (a renal cancer cell line with low FILNC1 expression) enhanced glucose starvation-induced cell death." (PMID 28978906, 2017). "Dysregulation of this regulatory circuitry, such as in renal cancer with decreased FILNC1 expression, leads to increased c-Myc protein levels, enhanced glucose uptake/lactate production and tumor development." (PMID 28978906, 2017). "FILNC1 knockdown suppresses apoptosis of renal cancer cells." (PMID 36230902, 2022). "Moreover, lncRNA FILNC1 plays a critical role in the energy metabolism and development of renal cancer through interacting with AUF1 to downregulate the expression of c-Myc, and low FILNC1 expression is associated with poor clinical outcomes." (PMID 34244473, 2021). "Finally, deficiency of FILNC1 in UMRC2 cells, another renal cancer cell line, similarly alleviated glucose starvation-induced cell growth suppression in vitro and enhanced renal tumor development in vivo." (PMID 28978906, 2017). "In renal cancer cells, for example, the FoxO transcription factor has a central role in tumor suppression through the stress-induced activation of FILNC1 (FoxO-induced long non-coding RNA 1)." (PMID 34298698, 2021). "Finally, FILNC1 knockdown in 786-O cells did not affect the levels of L-Myc or N-Myc, two other members of Myc family, under glucose starvation condition; indeed, L-Myc or N-Myc exhibited very low expression in the renal cancer cells used in this study." (PMID 28978906, 2017). "Consistent with the data that FILNC1 regulates the expression of glucose metabolism genes, computational analyses revealed a negative correlation between FILNC1 and ALDOC, or PDK1 in renal cancer." (PMID 28978906, 2017).
renal cell carcinoma (2 papers, 2017 to 2021). "Kidney-specific lncRNA FoxO-induced long non-coding RNA 1 (FILNC1) is downregulated in renal cell carcinoma correlating with poor clinical outcomes." (PMID 33652661, 2021). "FILNC1 is specifically expressed in kidney, and is downregulated in renal cell carcinoma; also, its low expression correlates with poor clinical outcomes in renal cell carcinoma." (PMID 28978906, 2017).
kidney cancer (1 paper, 2017). Primary or metastatic malignant neoplasm involving the kidney. "As FILNC1 is highly expressed in kidney tissue and is selectively downregulated in kidney cancer, it will be of great interest to examine whether FILNC1 could serve as a biomarker for tissue-of-origin tests and kidney cancer diagnostics." (PMID 28978906, 2017).
tumor (6 papers, 2017 to 2025). "In line with the data from in vitro analyses, our in vivo experiments using the xenograft model showed that FILNC1 deficiency promoted renal tumor development and markedly increased tumor size and weight at the endpoint." (PMID 28978906, 2017). "The ESR1-DAB2 cistromic-transcriptomic overlap revealed enrichment of RCAN1, which has an isoform (RCAN1.4) that has been associated with tumor suppression in one study, as well as an upstream negative regulator of Myc-1, FILNC1." (PMID 39207954, 2024). "FILNC1 is downregulated leading to increased c-MYC protein levels thereby increasing the glucose uptake, lactate production and tumor development." (PMID 33652661, 2021).
cancer (2 papers, 2017 to 2020). A tumor composed of atypical neoplastic, often pleomorphic cells that invade other tissues. "FILNC1 silencing in renal cancer cells lessens energy stress-induced apoptosis and considerably induces progression of this type of cancer." (PMID 33123468, 2020).